IL6 (interleukin 6)
Diseases named in the same sentence as IL6 in open-access papers (continued):
Sharing a sentence is not in itself a finding about the gene and the disease.
Obesity (continued). "IL-6 stimulates hepatic lipogenesis, and is associated with obesity, impaired insulin signaling, and altered insulin sensitivity by activating key steps in the insulin signaling pathway." (PMID 31921154, 2019). "Most findings in the literature are consistent regarding the association of obesity and higher levels of IL-6 and CRP, corroborating our results." (PMID 31071114, 2019). "Taken together, TNFα and IL-6 signaling in obesity-associated inflammation point towards complex, temporal, and cell-type-specific functions in the development of insulin resistance." (PMID 30591653, 2018). "Previously, chronic, unresolved inflammation in obesity has been linked to local and systemic production of pro-inflammatory cytokines, particularly C-reactive protein, IL-6, TNF-α, as well as chemotactic and adipokine signaling molecules." (PMID 29738558, 2018). "Obesity, sedentary behavior, and chronic inflammatory diseases such as RA are all associated with a chronic elevation in serum IL-6." (PMID 30587230, 2018). "In mouse models, it has been shown that HFDs and obesity can activate hepatic NF-κB which causes hepatic inflammation and increases the levels of IL-6, IL-1β, and TNF-α." (PMID 30026676, 2018). "Increased production of cytokines, such as interleukin-6 (IL-6) and IL-8, is regarded as diagnostic markers in inflammatory diseases including atherosclerosis, obesity, heart diseases, and sepsis." (PMID 29615908, 2018). "Though NASH is not always concomitant with ALT40, we supported our claim with the increased level of obesity-linked pro-inflammatory cytokines, IL-6 and TNF41." (PMID 30356113, 2018). "The contribution of TNFα and IL-6 signaling to obesity-associated insulin resistance is well studied in conditional mouse models, but still reveals contradictory outcomes." (PMID 30591653, 2018). "Two health behavior variables were positively and independently associated with IL-6 levels: current obesity (β = + 0.27, P = 0.0003) and tobacco consumption (β = + 0.43, P = 0.001 for former users; β = + 0.51, P = 0.0004 for current users)." (PMID 29951282, 2018). "High IL-6 levels have been associated with a variety of inflammation-associated diseases including rheumatoid arthritis, asthma and obesity." (PMID 30096932, 2018). "TNF-α upregulates obesity-induced IL-6 production and causes hepatic inflammation through activation of extracellular signal-regulated kinase (ERK) and signal transducers and activator of transcription 3 (Stat3) signaling." (PMID 30374329, 2018). "Chronically elevated baseline IL-6 plasma levels are associated with obesity, insulin resistance, and Type-2 diabetes." (PMID 30093853, 2018). "Obesity is associated with latent inflammatory responses indicated by an elevated expression of pro-inflammatory cytokines such as Il1, Il6, and TNFα." (PMID 30333974, 2018). "This is in line with our previous publication in which we postulated a STAT3-inducing factor in obesity to adopt IL-6 signaling in HCC development of IL-6Rα-deficient mice." (PMID 30224299, 2018). "A possible mechanism refers to obesity-associated inflammation and suggests that increased expression of proinflammatory cytokines, for example, interleukin-6 and tumor necrosis factor-α, is associated with cognitive decline." (PMID 30159333, 2018). "A study investigating the inflammatory characteristics of human IFP in knee OA and obesity demonstrated an overproduction of IL-6, which was associated with a decrease of local leptin secretion and an increase in adiponectin secretion." (PMID 29769086, 2018). "Among HNC patients, we also found a positive association between IL-6 and obesity, as defined by a BMI ≥ 30 kg/m2." (PMID 29951282, 2018). "Increased TNF-α and IL-6 production has been observed in adipose tissue taken from obese rodent or human subjects, and they have also been implicated as causative factors in obesity-associated insulin resistance and the pathogenesis of T2DM." (PMID 30914847, 2018).
Obesity (continued). "The association studies between obesity and the IL6 -174G >C polymorphism have shown higher BMI in the presence of C allele in cross-sectional and cohort studies, but it was not confirmed by meta-analysis." (PMID 30652031, 2018). "The aim of this paper was to assess the association of obesity measurements and IL-6, CRP and adiponectin." (PMID 29704817, 2018). "In univariate analyses leptin levels were positively associated with injury duration, BMI, fat mass, total lean mass, IL-6, and obesity status and were negatively associated with adiponectin and sarcopenia status." (PMID 29949600, 2018). "Decoding the activators and effectors of IL-6 in cardiac lipotoxicity during HFD-induced obesity will provide cues for treatment of obesity-associated dyslipidemia and cardiac lipotoxicity, and improve development of novel drug therapies." (PMID 30134607, 2018). "Leptin- (ob/ob) or LEPR-deficient (db/db) mice for instance are morbidly obese due to uncontrolled food intake, whereas animals deficient for IL-6 develop mature onset obesity." (PMID 30224299, 2018). "The G alleles of both IL-6 174 and IL-6 572 genes were associated with obesity and type 2 diabetes mellitus." (PMID 30338250, 2018). "Unaltered BW-gain in these cohorts during 8 months of maintenance is unexpected due to a previous publication, which demonstrates that IL-6-deficient mice develop mature onset obesity." (PMID 30224299, 2018). "The PPARG2 Pro12Ala (rs1801282) and IL6 -174G >C (rs1800795) have important function in body weight regulation and a potential role in obesity risk." (PMID 30652031, 2018). "While multiple factors contribute to obesity-associated cancers, we will only focus on the role of obesity-induced TNFα and IL-6 signaling in the promotion and development of hepatocellular carcinoma (HCC) and colorectal cancer (CRC) within this review." (PMID 30591653, 2018). "Levels of interleukin-1β, interleukin-6, interleukin-8, interferon-γ, and tumor necrosis factor-α were associated differently with patient-related characteristics (such as age, sex, obesity, and medical comorbidities)." (PMID 29581859, 2018). "Inflammation of adipose tissue in obesity is associated with increased IL-1β, IL-6 and TNF-α secretion and proposed to contribute to insulin resistance." (PMID 27840174, 2017). "Inflammatory mechanisms are linked with obesity and associated with the production of proinflammatory cytokines such as IL-6 and TNFα." (PMID 29269995, 2017). "Regarding IL-17, it was suggested that obesity predisposes to selective expansion of the Th17 subclass of T lymphocytes, producing high levels of IL-17 in an IL-6-dependent process." (PMID 29043005, 2017). "Obesity is also associated with a state of low-grade inflammation and elevated levels of IL-6, which has been commonly described in obese diabetic patients or only in obese individuals." (PMID 28225860, 2017). "Although IL-6 expression was below the detection limit in our experiment, low-grade inflammation is known as a major cause of obesity caused by the release of FFAs from adipocytes, related to the increased amount of adipose tissue." (PMID 28613268, 2017). "Obesity causes lipid accumulation in adipocytes that can increase the production of proinflammatory cytokines such as TNF-α, IL-6, and IL-1β, and this obesity-associated chronic low-grade inflammation leads to insulin resistance." (PMID 29082259, 2017). "Obesity is associated with an elevated secretion of proinflammatory cytokines, including IL-6, TNF-alpha, and C-reactive protein, and obesity is posited to be a state of chronic inflammation." (PMID 28428966, 2017). "Obesity and its associated metabolic endotoxaemia helps initiate a pro-inflammatory state characterised by raised serum IL-6 levels, which in turn is correlated with impairment of both Leydig (testosterone) and Sertoli cell function (AMH)." (PMID 28286655, 2017).
Obesity (continued). "Several studies demonstrated that systemic- IL-6 KO mice develop mature-onset obesity whereas adeno-associated viral delivery of IL-6 in rat hypothalamus or central over-expression of IL-6 decreased fat content and body weight gain." (PMID 28319140, 2017). "Nevertheless, some of these SNPs (rs1260326 (GCKR), rs13233571 (BCL7B), rs2847281 (PTPN2), and rs4129267 (IL6R) predicting hsCRP and rs630014 (ABO), rs651007 (ABO), and rs687289 (ABO) predicting IL-6) were associated with obesity-related traits." (PMID 28819125, 2017). "In the last decades, it was showed that IL-6-deficient mice developed mature-onset obesity with impaired glucose tolerance and increased glucose levels." (PMID 29062839, 2017). "It is generally accepted that depletion of IL-6 improves glucose regulation and obesity in mouse model and obesity-associated insulin resistance in type 2 diabetes in humans." (PMID 28706484, 2017). "CVD and cancer share risk factors such as obesity and diabetes mellitus and have common diagnostic biomarkers such as interleukin-6 and C-reactive protein." (PMID 29258216, 2017). "IL-6 is an inflammatory mediator of liver diseases, including obesity-associated fatty liver and cirrhosis." (PMID 26881746, 2016). "Production of IL-6 in adipose tissue has been shown to be increased during obesity and contributes to obesity-associated low-grade inflammation." (PMID 26661101, 2016). "With regard to impaired MPR, a prior study showed that Interleukin-6 (IL-6), a cytokine associated with obesity, can induce oxidative stress and endothelial dysfunction by upregulating the angiotensin II type 1 receptor." (PMID 27609091, 2016). "Inflammatory cytokine release from adipose tissue and elevated inflammatory cytokine levels including TNF-α and IL-6 have been associated with obesity." (PMID 27919232, 2016). "We show that impaired SC adipogenesis resulting in a reduced capacity to store triacylglycerols and accommodate energy in a physiological manner marks obesity-associated IR and is mediated, at least in part, through local secretion of IL-6." (PMID 27342408, 2016). "OSA is a systemic disease that causes an increase in TNF-α, IL-6, insulin resistance, and glucose intolerance; these inflammatory cytokines have also been implicated in the immunological mechanisms of obesity." (PMID 27408717, 2016). "Obesity was associated with higher levels of TNFα (p = 0.008), IL-6 (p<0.001), hsCRP (p<0.001), and adiponectin (p = 0.005)." (PMID 27459718, 2016). "It has recently been proposed that IL-1β is also associated with the proinflammatory response in obesity via the increased production of other cytokines, including IL-6." (PMID 27408717, 2016). "IL-15 induces the expression pro-inflammatory cytokines such as IL-6 and TNFα from macrophages that are implicated in the pathogenesis of obesity-associated metabolic syndrome." (PMID 27684068, 2016). "Obesity and T2D are associated with elevated plasma concentrations of IL-6, with adipose tissue being the major source under these conditions." (PMID 27148273, 2016). "This first report highlights that obesity combines an alteration in oral sensitivity to C18:2 with its association with an increased levels of IL-6 and leptin." (PMID 27413547, 2016). "In the mammary gland microenvironment specifically, obesity is directly linked with increased IL-6 signaling and increased macrophage recruitment compared to normal-weight mammoplasty specimens." (PMID 26884646, 2016). "Obesity-associated insulin resistance is marked by impaired SC adipogenesis, mediated, at least in a subset of individuals, by elevated local levels of IL-6." (PMID 27342408, 2016). "While IL-6 is often used as a marker for obesity-associated ‘meta-inflammation ’ measurement of plasma endotoxin levels (LPS), which were not assessed would be ideal and should be done in future studies." (PMID 26954359, 2016).
Obesity (continued). "Obesity was associated with higher sICAM-1 (p≤0.015), tumor necrosis factor-α (TNFα), interleukin-6 (IL-6), and high-sensitivity C-reactive protein (hs-CRP), p<0.001." (PMID 27459718, 2016). "In fact, increased circulating levels of pro-inflammatory mediators such as C-reactive protein (CRP), tumor necrosis factor α (TNFα), monocyte chemoattractant protein-1 (MCP-1) and interleukin-6 (IL-6) have been observed in obesity-associated IR." (PMID 27111539, 2016). "Obesity is also associated with increased serum levels of IL-6 and TNF-α, among other cytokines and chemokines." (PMID 26743937, 2016). "We suggest inflammation plays a central role in this relationship, as obesity features increases in inflammatory mediators such as C-reactive protein and interleukin-6, and chronic inflammation has been linked to worse stroke risk and outcome." (PMID 27655337, 2016). "The finding of higher levels of plasma CRP, TNF-a and IL-6 in the obese is also consistent with the findings of others suggesting the presence of chronic, systemic inflammation associated with obesity." (PMID 27513854, 2016). "We demonstrate that diet-induced obesity fosters the activation of tumor-associated macrophages and osteoclasts by bone marrow adipocytes via IL-6." (PMID 27049717, 2016). "Both obesity and metabolic syndrome are low-grade inflammatory disorders that were found to be associated with increased IL-6 and IgA values in previous studies in the same population." (PMID 26910567, 2016). "We and others have shown that serum IL-6 is associated with adiposity, suggesting that there is increased inflammation related to obesity as well." (PMID 27488495, 2016). "Obesity (BMI >30 kg/m2 or body fat ≥32% in females or ≥25% in males) was associated with higher sICAM-1 (p≤0.015), TNFα, IL-6, and hsCRP (p<0.001)." (PMID 27459718, 2016). "We also determined several notable adipokines implicated in obesity and obesity-related metabolic disorders, which included leptin, IL-6, TNF-α, and adiponectin." (PMID 27616737, 2016). "In a low grade inflammation linked to obesity, taste alteration is associated with high levels of IL-6 and leptin." (PMID 27413547, 2016). "Previous studies examining the putative association between variations in the promoter region of IL6 and risk of obesity in adults have yielded contradictive results, and studies among children are limited." (PMID 26558825, 2015). "Several studies implicated IL-6 as a co-inducer of the development of obesity-associated insulin resistance preceding the onset of type 2 diabetes." (PMID 25688211, 2015). "It has been suggested that IL-6 plays a role in the induction of the inflammatory process linked to obesity." (PMID 25897330, 2015). "A common SNP located in the promoter region of IL6, known as -174G > C (rs1800795, c.-237C > G) variant was associated with increased risk for overwheight and obesity-related metabolic disorders, especially insulin resistance in various group populations." (PMID 25897330, 2015). "Second, resveratrol strongly inhibited the obesity-associated and inflammation-dependent induction of IL-6, IL-8, and MCP-1 in SGBS adipocytes." (PMID 25926797, 2015). "Secondly, we only measured hsCRP, complements, and immunoglobulins as inflammatory markers but did not evaluate other markers such as tumor necrosis factor α and IL-6, which were potentially associated with obesity or type 2 diabetes." (PMID 26578821, 2015). "HFD-induced obesity in WT mice was associated with fatty liver and increased levels of IL-6 in serum and hepatic tissue." (PMID 26035386, 2015). "Early during infection (i.e., d3 p.i.), obesity was again associated with reduced production of cytokines IL-13, IL-5, IL-12p70, IFNγ, TNFα, IL6, and IL-1β, as well as IL-28b (IFNλ), IL-17, and IL-15." (PMID 26110868, 2015). "Common single nucleotide polymorphisms (SNPs) in adiponectin (ADIPOQ) and IL-6 (IL6) genes have been shown to be related to obesity and adiposity-related phenotypes." (PMID 25897330, 2015).
Obesity (continued). "Primary outcomes were obesity-associated hormones relevant to oesophageal adenocarcinoma risk (circulating concentrations of leptin, adiponectin, interleukin-6, tumour necrosis factor-alpha, C-reactive protein, and insulin resistance [HOMA])." (PMID 25706622, 2015). "High levels of interleukin-6 and haptoglobin are considered to be early biomarkers of inflammation associated with severe obesity with subsequent cardiovascular and type 2 diabetes risk." (PMID 27275205, 2015). "Reports on Mexican adolescents (age range: 14–19 years) found IL6 variants (rs1800795, rs1800796, and rs1800797) to associate with quantitative obesity-related traits and prevalence of obesity." (PMID 26558825, 2015). "Many authors emphasize associations between obesity and general inflammation with elevated levels of TNFα, IL-6, and leptins." (PMID 25663327, 2015). "Obesity is also a contributing factor; in obese women adiposity is associated with increased concentrations of inflammatory markers (IL-6, CRP, and adipokines) that correlate with depression and anxiety." (PMID 26089771, 2015). "Still, the IL-6 promoter polymorphism -174G/C has been related to the development of obesity and MetS." (PMID 25815341, 2015). "A recent study found that pre-pregnancy obesity was associated with increased expression of placental pro-inflammatory cytokines and circulating IL-6 by the end of pregnancy." (PMID 26569331, 2015). "Nevertheless, it seems that in obese children the C allele carriers have less subcutaneous fat and higher HDL-C concentrations, in contrast to the association of the IL-6 polymorphism -174G/C and obesity." (PMID 25815341, 2015). "We have investigated the relationship between ADIPOQ 45 T > G and IL6 -174G > C variants and obesity and metabolic markers in a sample of our population." (PMID 25897330, 2015). "High-sensitivity CRP is a more sensitive inflammatory marker associated with obesity indices than IL-6 and TNF-α." (PMID 24507240, 2014). "This is supported by studies showing that IL-6 deficient mice (IL-6−/−) develop mature onset obesity and have disturbed carbohydrate and lipid metabolism that is partly reversed by IL-6 replacement." (PMID 24563869, 2014). "In conclusion, this novel study showed that dietary fat intake, and the quality of the dietary fatty acids consumed, were associated with obesity risk and serum lipids differently, depending on the IL-6 genotype." (PMID 24962479, 2014). "Higher circulating concentrations of IL-6 have also been associated with obesity and visceral adipose tissue (VAT) deposition, lipid metabolism and increased risk for cardiovascular disease (CVD)." (PMID 24962479, 2014). "Continuous release of inflammatory mediators such as IL-6 perpetuates the inflammatory condition associated with obesity in PCOS, possibly contributing to insulin resistance and other long-term cardiometabolic risk factors." (PMID 25096410, 2014). "Not only has leptin been associated with obesity, but it has also been demonstrated to increase levels of cytokines such as IL-6 and IL-1b, cytokines that were also elevated in our study." (PMID 24732966, 2014). "Among all of these cytokines, IL-6 is both proinflammatory and a useful marker for obesity-associated inflammation." (PMID 24877058, 2014). "IL-6 has been linked to various pathological states, including obesity, and is secreted from a variety of different cells, including vascular endothelial cells." (PMID 24772421, 2014). "Obesity is often associated with increased markers of inflammation, in part because adipocytes themselves release adipokines, including IL‐6, TNF‐α, and CRP." (PMID 25347862, 2014). "Obesity is associated with a low-grade chronic systemic inflammation and in particularly interleukin-6 (IL-6), TNF-α and C-reactive protein (CRP) are present at high levels in the serum of obese people." (PMID 25386150, 2014).